THRA (thyroid hormone receptor alpha)
Description:
[Isoform Alpha-1]: Nuclear hormone receptor that can act as a repressor or activator of transcription. High affinity receptor for thyroid hormones, including triiodothyronine and thyroxine. [Isoform Alpha-2]: Does not bind thyroid hormone and functions as a weak dominant negative inhibitor of thyroid hormone action.
Synonyms: EAR7; ERBA1; NR1A1; THRA1; THRA2; EAR-7.1/EAR-7.2; THRA3; AR7; ERBA; TRalpha; TRalpha1; TRalpha2; c-ERBA-1; c-erbA; THRalpha; THRalpha1; THRalpha2; CHNG6; ERB-T-1
Tractability: Small molecule: an approved drug acts on it; a structure with a bound ligand is known; a high-quality ligand is known; it has a high-quality binding pocket; it belongs to a druggable protein family. PROTAC: ubiquitination databases record sites on it; its protein half-life has been measured; a small molecule that binds it is known.
Target class: Nuclear hormone receptor subfamily 1 group A; Transcription factor; Nuclear hormone receptor subfamily 1 group A member 1; Nuclear receptor; Nuclear hormone receptor subfamily 1
Gene: Protein-coding gene on chromosome 17 (40,058,290 to 40,093,867, forward strand). Ensembl gene ENSG00000126351.
Subcellular location: Nucleus; Cytoplasm (Isoform Alpha-2)
Subcellular location (Human Protein Atlas): Cytosol
Pathways (Reactome):
Gene expression (Transcription): Nuclear Receptor transcription pathway
Metabolism of proteins: SUMOylation of intracellular receptors
Gene Ontology:
Molecular function: DNA-binding transcription factor activity; general transcription initiation factor binding; nuclear receptor activity; protein binding; protein domain specific binding; TBP-class protein binding; thyroid hormone binding; transcription cis-regulatory region binding; DNA-binding transcription factor activity, RNA polymerase II-specific; RNA polymerase II cis-regulatory region sequence-specific DNA binding; chromatin DNA binding; DNA binding; protein-containing complex binding; sequence-specific DNA binding; zinc ion binding
Biological process: hormone-mediated signaling pathway; negative regulation of DNA-templated transcription; negative regulation of DNA-templated transcription initiation; negative regulation of RNA polymerase II transcription preinitiation complex assembly; regulation of transcription by RNA polymerase II; transcription by RNA polymerase II; cell differentiation; negative regulation of transcription by RNA polymerase II; positive regulation of cold-induced thermogenesis; positive regulation of transcription by RNA polymerase II; retinoic acid receptor signaling pathway; thyroid hormone receptor signaling pathway; mRNA transcription by RNA polymerase II; positive regulation of thyroid hormone receptor signaling pathway; regulation of DNA-templated transcription
Cellular component: cytosol; nucleus; chromatin; cytoplasm; nucleoplasm; RNA polymerase II transcription regulator complex
Genetic constraint (gnomAD): Loss-of-function variants: 13 observed, 47.03 expected, observed/expected ratio (o/e) 0.28, 90% interval 0.18 to 0.44. The upper end of that interval is the gene's LOEUF score, 0.44, which puts it in group 1 of 6, group 1 being the genes least tolerant of losing a copy. Missense variants: 278 observed, 582.78 expected, observed/expected ratio (o/e) 0.48, 90% interval 0.43 to 0.53. Synonymous variants: 195 observed, 224.88 expected, observed/expected ratio (o/e) 0.87, 90% interval 0.77 to 0.98.
Homologues: Orthologues: mouse Thra (99% identical), chimpanzee THRA (93% identical), guinea pig THRA (93% identical), rabbit THRA (93% identical), rat Thra (92% identical), macaque THRA (90% identical), pig THRA (89% identical), tropical clawed frog thra (87% identical), zebrafish thrab (85% identical), zebrafish thraa (82% identical), dog THRA (80% identical), Drosophila melanogaster EcR (25% identical), and 184 more. Paralogues in human: THRB (67% identical), NR1D2 (29% identical), RARB (29% identical), RARA (28% identical), RARG (28% identical), RORA (27% identical), RORC (27% identical), NR1D1 (26% identical), NR1H3 (26% identical), NR1H4 (26% identical), PPARA (25% identical), RORB (24% identical), and 6 more.
Diseases named in the same sentence as THRA in open-access papers:
THRA is named in the same sentence as 77 diseases in open-access papers, as found by Europe PMC text mining. Sharing a sentence is not in itself a finding about the gene and the disease. The quoted sentences say what the papers report.
breast carcinoma (18 papers, 1989 to 2024). "The thyroid hormone receptor alpha-2 (THRα-2) has been found to be positively associated with several prognostically favorable tumor factors and a lower mortality in breast cancer." (PMID 34930399, 2021). "THRα, which is known to dimerize with RARβ, has also previously been implicated to have a potential tumour suppressor role in breast cancer tissues, confirmed using western blot analysis." (PMID 25934412, 2015). "The results of the present study support the hypothesis that a low tumor-specific THRα-2 expression is associated with prognostically unfavorable tumor characteristics and via those associations also a higher mortality in breast cancer." (PMID 34930399, 2021). "Thyroid hormone receptor alpha-2 (THRα-2) acts as an antagonist for triiodothyronine (T3) signaling, and a low expression has been associated with unfavorable tumor characteristics and a higher mortality in breast cancer." (PMID 34930399, 2021). "Previous research has suggested that thyroid hormone receptor alpha 1 (THRα1), a hormone responsive splice variant, may play a role in breast cancer progression." (PMID 30410118, 2018). "This demonstrated that higher expression of both THRα and THRα1 are associated with a decrease in overall survival in women with triple negative (basal like) breast cancer, and also identified a novel prognostic association with THRα3 in basal-like and luminal A subtype." (PMID 30410118, 2018). "Among antiarrhythmics, dronedarone has shown also anticancer effects through antagonizing the thyroid hormone receptor alpha 1 (THRα1) that seems to play a role in breast cancer progression." (PMID 35268508, 2022). "Our study, for the first time, identified THRα expression in human breast cancer specimens in regard to focality." (PMID 33478016, 2021). "There was a higher breast cancer-specific mortality among women with low, compared with high, THRα-2 tumor expression, HR 1.38 (95% CI 0.96–1.99) for all of follow-up and HR 1.52 (95% CI 1.03–2.24) for the period 0–15 years." (PMID 34930399, 2021). "We found evidence of higher breast cancer-specific mortality among women with low expression of tumor-specific THRα-2 compared with those with high expression." (PMID 34930399, 2021). "Nevertheless, our study, for the first time, identified THRα expression in human breast cancer specimens concerning focality." (PMID 33478016, 2021). "In the Kaplan–Meier graph, an increased breast cancer-specific mortality was observed in the group with low compared to high THRα-2 expression, up until 18 years of follow-up, at which point the two curves converged (log-rank p = 0.08)." (PMID 34930399, 2021). "Our findings are congruent with previous outcomes regarding THRα expression and its effect on survival analysis in breast cancer." (PMID 33478016, 2021). "This is by far the largest study investigating THRα-2 expression and breast cancer, and the present findings are in line with previous research." (PMID 34930399, 2021). "Furthermore, our results indicate that ER-status might interact with THRα-2, with a positive association between overall and breast cancer specific survival and THRα-2 status among women with ER-positive tumors and an inverse association among women with ER-negative tumors." (PMID 34930399, 2021). "The up-regulation of FOXJ3 in multiple types of cancers and the link between THRA and the breast cancer prognostic prediction suggest oncogenic functions of these two transcription factors, which is opposite to that of 7SK." (PMID 33868377, 2021). "In breast cancer, previous studies showed that higher levels of the thyroid hormone receptor alpha were an independent prognostic factor for increased overall survival." (PMID 32807826, 2020). "The expression of other isoforms of THRα were also characterized; THRα4 is infrequently expressed in the TCGA breast cancer data (Sup." (PMID 30410118, 2018).
breast carcinoma (continued). "The levels of both RARβ and THRα gene expression were also found to be decreased in breast cancer patients compared to controls (p < 0.001)." (PMID 25934412, 2015). "This protein also has been shown to have a potential tumour suppressor role in breast cancer and is known to dimerize with Thyroid hormone receptor alpha (THRα)." (PMID 25934412, 2015). "Expression levels of RARβ and THRα were previously reported by this group, on a total of n = 100 breast tissues, consisting of n = 75 breast cancers, n = 10 fibroadenoma tissues and n = 15 normal breast tissues." (PMID 25934412, 2015). "Since then, several genetic analyses have shown some interplay between BRCA1 and THRA genes in breast cancers." (PMID 23805307, 2013). "We found evidence of increased breast cancer-specific mortality for women with low THRα-2, HR 1.38 (95% CI 0.96–1.99), which remained after adjusting for age at diagnosis, HR 1.48 (95% CI 1.03–2.14), but not after adjusting for relevant prognostic factors, HR 0.98 (95% CI 0.66–1.45)." (PMID 34930399, 2021). "Low tumor-specific THRα-2 expression was in this study associated with prognostically unfavorable tumor characteristics and a higher mortality in breast cancer, but not independent from other prognostic factors." (PMID 34930399, 2021). "Given a growing body of literature which supports the role of THRα and its splice variants as prognostic biomarkers for overall survival among women with breast cancer, we investigated the prognostic significance of THRα and THRα1 expression in the well-annotated TCGA breast cancer cohort." (PMID 30410118, 2018). "Although there are trends that overall survival is shorter in women with high levels of both THRα and THRα1, especially in women with triple negative and luminal A breast cancer, the number of events in each group may limit the power of this analysis." (PMID 30410118, 2018). "Furthermore, this research group investigated the involvement of other nuclear receptors, such as vitamin D receptor, retinoid X receptor, thyroid hormone receptor alpha 1 (THRα1), and thyroid hormone receptor alpha 2 (THRα2), in the prognosis of MF/MC breast cancer patients." (PMID 37349265, 2023). "We believe that our data-driven method is preferable in this situation; however, as more research is presented regarding THRα-2 expression and breast cancer, a standardized and pre-defined histological evaluation and cutoff could minimize bias introduced by researchers in the data." (PMID 34930399, 2021). "Thus, it still remains unclear what pathways THRα-2 might affect in breast cancer cells." (PMID 34930399, 2021). "The reason for applying that methodology was that the field is rather unexplored, and there is no standardized threshold for THRα-2 expression in breast cancer." (PMID 34930399, 2021). "In the present study, we used TMA to evaluate the THRα-2 expression, and as the receptor is not extensively studied in breast cancer, the tumor-specific heterogeneity is not known." (PMID 34930399, 2021). "These experiments were technically successful yet did not demonstrate that THRα1 or THRα mRNA depletion impaired breast cancer cell growth or survival." (PMID 30410118, 2018). "The results indicate that THRα-2 might be a prognostic marker in breast cancer, but not independent from other prognostic markers." (PMID 34930399, 2021). "Thus, a low THRα-2 expression acts as a marker of more extensive disease, but it is not an independent predictor of survival in breast cancer." (PMID 34930399, 2021). "However, the effect of modulation of THRα and specific isoforms in breast cancer has not been characterized." (PMID 30410118, 2018). "Thus, we conclude that dronedarone’s cytotoxic effect in breast cancer cell lines are independent of THRα or THRα1 antagonism." (PMID 30410118, 2018).
breast carcinoma (continued). "In both cases, broadlyaccepted breast cancer drivers such as BRCA1 and ESR1 are central nodes in the network.The network analysis has revealed severalinfluential DCDs that are not curated CGC genes yet, for example E2F2 and THRA fromsingle-cell, and SIN3A from bulk data." (PMID 36124841, 2022).
hypothyroidism (8 papers, 2015 to 2025). Abnormally low levels of thyroid hormone. "THRA is known to be related to erythropoiesis, and its mutation displays the characteristics of hypothyroidism, anemia, and abnormal bone growth." (PMID 34445011, 2021). "THRA and THRB mutations directly caused abnormal thyroid hormone levels, which was associated with tissue-specific hypothyroidism." (PMID 33959028, 2021). "While our results revealed that both the fetal LVR and KID express THRA and THRB, gene expression of IGFBPs in the fetal LVR was much more perturbed by the impact of fetal hypothyroidism." (PMID 40693299, 2025). "As a result of SNP filtering, 18, 18, 18,18,5,17,17,17,17,17 and 4 SNPs were included for GD, HT, hypothyroidism, hyperthyroidism, TC, TSH, TRH, THRα, TP, TG and TBG, respectively, in final analysis." (PMID 39205687, 2024). "After removing palindromic SNPs and outliers, we obtained 26, 12, 65,11,258,22,26,16,20, and 23 SNPs for GD, HT, hypothyroidism, hyperthyroidism, TC, TSH, TRH, THRα, TP and TG, respectively." (PMID 39205687, 2024). "MR analysis showed that there had no causal association between AA and GD, HT, Hypothyroidism, Hyperthyroidism, TC, TSH, TBG, THRα, TP, TG and TBG." (PMID 39205687, 2024). "MR analysis showed that there had no causal association between PSC and hypothyroidism, AT, TC, TSH, TRH, TBG, THRα, TP and TG." (PMID 37928559, 2023). "Hence, the active compouds of AMR have direct interaction with THRA and THRB targets, and up-regulated the T3 and T4 levels to alleviate hypothyroidism." (PMID 33959028, 2021). "Meanwhile, the results of network pharmacology indicated that THRA and THRB might be potential therapeutic targets for hypothyroidism." (PMID 33959028, 2021). "However, there was no causal effect between PSC and AT, hypothyroidism, TC, TSH, TRH, TBG, THRα, TP, TG." (PMID 37928559, 2023).
congenital hypothyroidism (6 papers, 2014 to 2024). A thyroid hormone deficiency present from birth. "Increased head circumference was indeed observed in 20% of patients, and has also been reported in other causes of congenital hypothyroidism and in patients with resistance to thyroid hormone due to a mutation in the THRA gene." (PMID 26840047, 2016). "In humans, a role for TR-α1 in brain development is supported by descriptions of patients with cognitive impairment phenotypes similar to those observed in congenital hypothyroidism who harbor primary mutations in the THRA gene." (PMID 24904526, 2014). "Thyroid hormone receptor alpha (THRA) is related to congenital hypothyroidism." (PMID 36624383, 2023). "Thyroid hormone resistance due to MCT8, THRα, and SECISBP2 defects may lead to a severe developmental delay like congenital hypothyroidism, but is characterized by normal TSH and partially normal T3 and T4 levels." (PMID 39201272, 2024).
Obesity (5 papers, 2007 to 2025). Accumulation of substantial excess body fat. "T3 causes harmful effects on the bone and cardiac system by binding to THRα, which is a major barrier to its use as an obesity treatment." (PMID 39107484, 2024). "The network shows that RXRA interacts with proteins related to a tumor (THRA related to pituitary adenome) and those related to certain diseases caused by abnormalities in lipid metabolism (e.g., NR0B2 related to obesity, PPARA to hyperapobetalipoproteinemia, and PPARGC1A to lipodystrophy)." (PMID 17705877, 2007).
hyperthyroidism (4 papers, 2023 to 2025). Overactivity of the thyroid gland resulting in overproduction of thyroid hormone and increased metabolic rate. "Being concerned about the impact of THs on THRα in the heart, we decided to proceed with this case similarly to patients with hyperthyroidism, where antithyroid drugs are recommended as a fundamental treatment and preoperative approach." (PMID 40004739, 2025). "However, the simultaneous occurrence of a severe complex heart defect and RTH in a child presenting with selective clinical symptoms of hyperthyroidism prompted us to apply atypical preoperative treatment (antithyroid drugs), which resulted in the normalisation of TH effects on the THRα." (PMID 40004739, 2025). "The drug’s selectivity for the target receptor is crucial to mitigate the levothyroxine-induced issue of binding to both THRα and THRβ, which would otherwise lead to hyperthyroidism in non-target tissues." (PMID 40217851, 2025). "However, there was no causal relationship between GD, hyperthyroidism, TC, TSH, TRH, TBG, THRα, TP, TG, and AA." (PMID 39205687, 2024). "Due to the differential distribution and function of TH receptors in various tissues, affected individuals may exhibit symptoms of both hypothyroidism (e.g., short stature) and/or hyperthyroidism (e.g., tachycardia—heart rate depends on the effect of THs on the non-defective THRα)." (PMID 40004739, 2025).
thyroid (4 papers, 2012 to 2025). "Next, we tested the percentiles for the fT3/fT4 ratio for their discriminatory power between pathologies that are either thyroid-related (e.g., in patients with mutations in THRA, SLC16A2, or SECISBP2) or not (e.g., in patients with cerebral palsy)." (PMID 39201272, 2024). "Alterations in the genes of these receptors (THRA, THRB and TSHR) have been related to thyroid diseases, including thyroid cancer." (PMID 23781307, 2012).
thyroid cancer (4 papers, 2012 to 2025). "Three studies have reported the association of genetic variants in the THRA gene with thyroid cancer risk, but the conclusions are limited by the small size of the populations studied." (PMID 23781307, 2012). "In the case of the THRA gene, for the rs939348 polymorphism, the logistic regression analysis (co-dominant model) showed an increase in the risk of thyroid cancer." (PMID 23781307, 2012). "In this study, we have examined a THRA polymorphism that maps in the 5′-UTR region, far away from the 3′-UTR CA repeat analysed in the previous studies, and our results also indicated a role for the THRA gene in thyroid cancer risk." (PMID 23781307, 2012). "Given the limited information concerning the implication of genes involved in the thyroid function on thyroid cancer risk, in this study, we have analysed the risk association between common genetic variants in the THRA, THRB and TSHR genes and DTC in a large Spanish population." (PMID 23781307, 2012). "Given the functional relationship between THRA, THRB, TSHR and TRHR, we decided to evaluate the combined effect of common genetic variants of these genes on thyroid cancer susceptibility." (PMID 23781307, 2012). "In three earlier reports, the dinucleotide CA repeated in the 3′-noncoding region of THRA was found to be related to thyroid cancer." (PMID 23781307, 2012). "Our results confirm that THRA is a risk factor for DTC, and we show for the first time the combined effect of THRB and TG or TRHR on DTC susceptibility, supporting the importance of gene–gene interaction in thyroid cancer risk." (PMID 23781307, 2012). "In contrast, no mutations in the THRA gene have been described in thyroid tumours; thus, the specific function of THRA in thyroid cancer remains unclear." (PMID 23781307, 2012). "Although mutations in the TR genes, THRA and THRB, are not common in thyroid tumours, a decreased expression of these genes has been found in thyroid cancer." (PMID 23781307, 2012).